SSX2IP (SSX family member 2 interacting protein)
Description:
Belongs to an adhesion system, which plays a role in the organization of homotypic, interneuronal and heterotypic cell-cell adherens junctions (AJs). May connect the nectin-afadin and E-cadherin-catenin system through alpha-actinin and may be involved in organization of the actin cytoskeleton at AJs through afadin and alpha-actinin (By similarity). Involved in cell movement: localizes at the leading edge of moving cells in response to PDGF and is required for the formation of the leading edge and the promotion of cell movement, possibly via activation of Rac signaling (By similarity). Acts as a centrosome maturation factor, probably by maintaining the integrity of the pericentriolar material and proper microtubule nucleation at mitotic spindle poles. The function seems to implicate at least in part WRAP73; the SSX2IP:WRAP73 complex is proposed to act as regulator of spindle anchoring at the mitotic centrosome. Involved in ciliogenesis. It is required for targeted recruitment of the BBSome, CEP290, RAB8, and SSTR3 to the cilia.
Synonyms: ADIP; hMsd1
Tractability: PROTAC: ubiquitination databases record sites on it.
Gene: Protein-coding gene on chromosome 1 (84,643,706 to 84,690,955, reverse strand). Ensembl gene ENSG00000117155.
Subcellular location: Cell junction, adherens junction; Nucleus; Cytoplasm, cytoskeleton, microtubule organizing center, centrosome, centriolar satellite; Cytoplasm, cytoskeleton, cilium basal body
Subcellular location (Human Protein Atlas): Basal body; Centriolar satellite; Centrosome; Acrosome; Equatorial segment; Principal piece
Gene Ontology:
Molecular function: protein binding; protein domain specific binding
Biological process: centrosome cycle; cilium assembly; intraciliary transport involved in cilium assembly
Cellular component: centriolar satellite; centrosome; ciliary basal body; protein-containing complex; adherens junction; nucleus
Genetic constraint (gnomAD): Loss-of-function variants: 46 observed, 69.15 expected, observed/expected ratio (o/e) 0.67, 90% interval 0.52 to 0.85. The upper end of that interval is the gene's LOEUF score, 0.85, which puts it in group 3 of 6, group 1 being the genes least tolerant of losing a copy. Missense variants: 548 observed, 607.58 expected, observed/expected ratio (o/e) 0.9, 90% interval 0.84 to 0.97. Synonymous variants: 202 observed, 210.99 expected, observed/expected ratio (o/e) 0.96, 90% interval 0.85 to 1.08.
Homologues: Orthologues: chimpanzee SSX2IP (99% identical), macaque SSX2IP (98% identical), dog SSX2IP (95% identical), pig SSX2IP (93% identical), guinea pig SSX2IP (90% identical), mouse Ssx2ip (88% identical), rat Ssx2ip (87% identical), rabbit SSX2IP (69% identical), tropical clawed frog ssx2ip (53% identical), zebrafish ssx2ipa (47% identical), zebrafish ssx2ipb (40% identical).
Diseases named in the same sentence as SSX2IP in open-access papers:
SSX2IP is named in the same sentence as 17 diseases in open-access papers, as found by Europe PMC text mining. Sharing a sentence is not in itself a finding about the gene and the disease. The quoted sentences say what the papers report.
acute myeloid leukemia (7 papers, 2010 to 2022). Acute myeloid leukemia (AML) is a group of neoplasms arising from precursor cells committed to the myeloid cell-line differentiation. "Many studies reported that SSX2IP as an acute myeloid leukemia-associated antigen, is a potential immunotherapy target for leukemia." (PMID 36199443, 2022). "Synovial sarcoma, X breakpoint 2 interacting protein (SSX2IP), which has been identified as an acute myeloid leukemia associated antigen, is a potential target for leukemia immunotherapy." (PMID 23452395, 2013). "Many studies indicated that SSX2IP is an acute myeloid leukemia-associated antigen and a potential immunotherapy target for leukemia." (PMID 23826132, 2013). "Importantly, since SSX2IP has been identified as an acute myeloid leukaemia-associated antigen and a potential immunotherapy target for leukemia, this study has expanded the usage of those SSX2IP related applications to HCC." (PMID 23452395, 2013). "It was one of the first tumor antigens used as a biomarker for improved overall survival, since an elevated expression of the SSX2IP predicts survival in acute myeloid leukemia patients who lack detectable cytogenetic rearrangements." (PMID 35328721, 2022). "A previous GEP study demonstrated an altered SSX2IP expression in patients with acute myeloid leukemia based on cytogenetic translocations." (PMID 33921415, 2021). "Moreover, the overexpression of SSX family member 2 interacting protein (SSX2IP) has been documented in patients with acute myeloid leukemia (AML) and found to promote metastasis and chemotherapeutic resistance in hepatocellular carcinoma cells." (PMID 35008958, 2022). "Previous studies indicated that SSX2IP is an acute myeloid leukemia-associated antigen, as analysis of clinical cases showed that the expression of SSX2IP was identified in the serum of 33% patients with acute myeloid leukaemia (AML), but not in healthy volunteers." (PMID 23452395, 2013).
leukemia (7 papers, 2007 to 2025). A malignant (clonal) hematologic disorder, involving hematopoietic stem cells and characterized by the presence of primitive or atypical myeloid or lymphoid cells in the bone marrow and the blood. "Studies of SSX2IP in tumor-related fields have been focused on leukemia in the past, while little is known about its role in oncology of other types of cancers." (PMID 23452395, 2013). "SSX2IP contributes to centrosome maturation and is overexpressed in leukemia." (PMID 40861419, 2025). "In human leukemias, SSX2IP appeared to be expressed in cell cycle-regulated patterns." (PMID 20981248, 2010). "In addition these studies identified known leukemia antigens such as RHAMM, MAGE-A1 as well as novel targets for leukemia immunotherapy such as PASD1, SSX2IP and BAGE." (PMID 19662193, 2007). "Since SSX2IP is expressed mainly on AML blast in the process of proliferation, it may be suitable to play a dual role as a predictor of overall survival and also as target for immunotherapy in leukemia." (PMID 35328721, 2022).
hepatocellular carcinoma (6 papers, 2013 to 2024). A malignant tumor that arises from hepatocytes. "Consistently in abdominal cavity metastasis and liver metastasis models of immune-deficient mice, SSX2IP was able to promote the metastasis of hepatoma cells." (PMID 23452395, 2013). "SSX2IP promoted the tumorgenesis and progression of hepatocellular carcinoma and contributed to the drug resistance, enabling it a new biomarker and specific target in hepatocellular carcinoma." (PMID 33789615, 2021). "At the cytological level, SSX2IP stimulates the wound healing, metastasis and invasion of hepatoma cells, and reduces the sensitivity of hepatoma cells to 5-Fu and CDDP." (PMID 23452395, 2013). "Given the functionality prompts of SSX2IP and its homologue gene ADIP, we decided to explore the role of SSX2IP in the development and progression of hepatocellular carcinoma." (PMID 23452395, 2013). "Our results suggest that SSX2IP can significantly promote the motility, invasion and migration of hepatoma cells and improve their resistance to chemotherapeutic drugs." (PMID 23452395, 2013). "Hepatoma cells with high expression of SSX2IP were shown a very strong mobility, and the number of cells which had penetrate the filter membrane in this group was significantly higher than in the parental and empty vector-transfected groups." (PMID 23452395, 2013). "Statistical analysis of pathological features and postoperative survival of clinical cases of hepatocellular carcinoma patients demonstrated that tumor with SSX2IP high expression had inclinations towards larger tumor size and more tumor thrombus." (PMID 23452395, 2013). "Our studies showed that SSX2IP can promote the development and metastasis of hepatocellular carcinoma." (PMID 23452395, 2013). "SSX2IP was reported promoting metastasis and chemotherapeutic resistance in hepatocellular carcinoma and relating poor outcomes of nasopharyngeal carcinoma, while LOC102724892 is a lncRNA gene whose function remains unknown." (PMID 35042519, 2022). "Moreover we examined the influence of SSX2IP overexpression on the chemosensitivity of hepatocellular carcinoma cells to two most common chemotherapy drugs (5-Fu and CDDP) using Cell counting kit-8 (CCK-8)." (PMID 23452395, 2013). "The results clearly reveal a promoting role of SSX2IP in hepatocellular carcinoma development." (PMID 23452395, 2013). "Importantly, SSX2IP was shown in our previous studies to promote the motility, invasion and migration and chemotherapy resistance of hepatoma cells, indicating its important role in the development and metastasis." (PMID 23826132, 2013). "Taken together, our patient cases studies suggest that SSX2IP may have a previously unrecognized role in promoting hepatocellular carcinoma." (PMID 23452395, 2013). "A hepatocellular carcinoma research study has reported that the SSX2IP gene can induce the occurrence and metastasis of cancer cells and that the survival time in the SSX2IP high expression group is shorter than that in the low expression group (p = 0.004) of 51 HCC patients." (PMID 38893126, 2024). "Our data showed SSX2IP reduced the sensitivity of hepatoma cells to 5-Fu and CDDP and significantly increased IC50, which indicated that SSX2IP may be a resistance related gene with the ability to promote the resistance of hepatoma cells to chemotherapeutic drug." (PMID 23452395, 2013).
nasopharyngeal carcinoma (3 papers, 2021 to 2024). A carcinoma arising from the nasopharyngeal epithelium. "High levels of SSX2IP were associated with aggressive pathological features and poor outcomes in nasopharyngeal carcinoma." (PMID 33789615, 2021).
breast carcinoma (2 papers, 2022 to 2023). "Six hub genes (PSMC6, AURKB, CASP9, BAD, ZNF24, and SSX2IP) that were significantly associated with the prognosis of breast cancer." (PMID 36199443, 2022). "We then identified six hub genes (PSMC6, AURKB, CASP9, BAD, ZNF24, and SSX2IP) that were significantly associated with the prognosis of breast cancer." (PMID 36199443, 2022). "To further clarify the interaction between DEGs, we screened fifteen hub genes by constructing the PPI network, among which the expression of PSMC6, AURKB, CASP9, BAD, ZNF24, and SSX2IP was associated with OS in breast cancer patients, which attracted our attention." (PMID 36199443, 2022). "For instance, NDST1, FRZB, ALAD, EDNRB, SSX2IP, and SFN have strong associations with breast cancer development, which bolsters our confidence in the viability of our model." (PMID 38007443, 2023).
gastric cancer (2 papers, 2013 to 2022). A primary or metastatic malignant neoplasm involving the stomach. "It is also speculated that SSX2IP plays an important role in the development and metastasis of gastric cancer and liver cancer." (PMID 36199443, 2022). "miR-338-3p is down regulated in gastric cancer and SSX2IP is supported to a target gene of miR-338-3p, it promoted us to speculate that SSX2IP might be overexpression in gastric cancer tissues and relative to matched non-tumor tissues." (PMID 23826132, 2013). "Thus, the analysis of the expression of miR-338-3p and SSX2IP in gastric cancer tissues confirmed the existence of inverse correlation between the expression of miR-338-3p and its target gene SSX2IP (Person Chi-square test: P<0.001, Spearman Correlation: r = -0.442, P<0.001)." (PMID 23826132, 2013).
liver cancer (2 papers, 2022). An epithelial or non-epithelial malignant neoplasm that arises from the liver. "There are several reasons for the poor treatment outcomes in patients with advanced liver cancer, including the natural drug resistance of liver cancer cells and the high expression of various proteins, such as P-glycoprotein and SSX2IP, which promote drug resistance." (PMID 35127582, 2022).
myeloid leukemia (1 paper, 2018). A clonal proliferation of myeloid cells and their precursors in the bone marrow, peripheral blood, and spleen. "Our previous serological analysis of recombinant tumor cDNA expression libraries (SEREX) analysis of AML patient sera, identified SSX2IP and PASD1, as well as SSX2IP’s interacting partner, SSX2, as potential targets for the immunotherapy of myeloid leukemia." (PMID 29423088, 2018).
osteosarcoma (1 paper, 2015). A usually aggressive malignant bone-forming mesenchymal neoplasm, predominantly affecting adolescents and young adults. "In agreement with our previous findings, ultraviolet irradiation of human U2OS osteosarcoma cells led to a quantitative loss of CEP131, PCM1 and SSX2IP from CS in a p38-dependent manner." (PMID 26616734, 2015).
sarcoma (1 paper, 2017). A usually aggressive malignant neoplasm of the soft tissue or bone. "Up to date, it has been shown that miR-338 respectively targeted proto-oncogenes smoothened (SMO), Phosphatidylinositol-3,4,5-trisphosphate-dependent Rac exchange factor 2 (PREX2a), synovial sarcoma and X breakpoint 2 interacting protein (SSX2IP) respectively in several solid tumors." (PMID 28423738, 2017).
cancer (10 papers, 2009 to 2026). A tumor composed of atypical neoplastic, often pleomorphic cells that invade other tissues. "SSX2IP encoded Synovial Sarcoma X breakpoint 2 Interacting Protein (SSX2IP) has been revealed to play various roles in human cancers." (PMID 33789615, 2021). "The involvement of SSX2IP in multiple cancers reinforces the biological and physiological significance of the miR-338-3p/SSX2IP cascade in cancer development, and has prompted us to further investigate the status of miR-338-3p/SSX2IP in other types of cancers." (PMID 23826132, 2013). "Further analysis of SSX2IP was recently reported by Breslin and colleagues in a review on SSX2IP and its emerging role in cancer." (PMID 20981248, 2010). "Thus, we concluded that the cancer suppressor function of miR-338-3p in GC is at least partially through suppressing its target gene SSX2IP." (PMID 23826132, 2013). "Interestingly, RAB3IP is found on chromosome 12q13-14, a region known to be frequently rearranged or amplified in human cancers, and SSX2IP is on 1p22 also in a region commonly deleted, amplified, or translocated in human tumors." (PMID 20981248, 2010). "Consistently, the expression of CDKN1C and KIT was lower in cancers, including KIRC, KIRP, and BRCA, while ICAM1, SSX2IP, and TNFSF10 were higher in cancers, including STAD and CESC, opposing the effects of miR-221/222-3p." (PMID 41602427, 2026). "Therefore, we would like to focus our discussion on genes that have been reported in cancer research, such as ESRP2, MUC17, MYH10, and SSX2IP." (PMID 38893126, 2024). "Intriguingly, upon MSD1/SSX2IP depletion in U2OS and many other cancer cells, satellite aggregates contain, besides constitutive satellite components, a number of structural constituents of centrioles/centrosomes that are not normally localised to centriolar satellites." (PMID 27484406, 2017).
tumor (6 papers, 2013 to 2023). "Among them, 32 samples showed a ~2-fold up-regulation of SSX2IP compared with the matched non-tumor controls." (PMID 23452395, 2013). "Here we identified SSX2IP as an important novel target of miR-338-3p, and provided both cytological and histological evidence suggesting the tumor-promoting role of SSX2IP in GC." (PMID 23826132, 2013). "Statistical analysis of clinical cases revealed that the SSX2IP high expression group had inclinations towards larger tumor size, more tumor thrombus and shorter survival period, implying a strong correlation between the expression level of SSX2IP and HCC tumorigenesis." (PMID 23452395, 2013). "Importantly, the SSX2IP high expression group had inclinations towards larger tumor size and more tumor thrombus (P < 0.05)." (PMID 23452395, 2013). "We also show that miR-338-3p may function as an tumor suppressor by directly targeting SSX2IP." (PMID 23826132, 2013). "Therefore, it is suggested that SSX2IP may regulate the EMT-MET by affecting E-cadherin-catenin systems and thereby promote the invasion and metastasis of tumor cells." (PMID 23452395, 2013).
SSX2IP also shares sentences with these, for which no sentence is quoted: cardiovascular diseases (1 paper); dyslipidemia (1); Insulin resistance (1); ovarian carcinoma (1); type 2 diabetes (1).